GPC1 (glypican 1)
Diseases named in the same sentence as GPC1 in open-access papers (continued):
Sharing a sentence is not in itself a finding about the gene and the disease.
Hepatitis (1 paper, 2021). Inflammation of the liver. "Thirdly, in the risk factor (alcohol consumption and hepatitis) subgroup, the expression levels of GPC-1, 2, and 3 in the hepatitis group were related to the poor prognosis of HCC." (PMID 33902495, 2021). "Among them, GPC-1 was related to the prognosis of HCC in pathological stage, grade, AJCC, vascular invasion, sex, race, risk factors (alcohol consumption and hepatitis) subgroups, and the expression level of GPC-1 was negatively correlated with the OS of HCC." (PMID 33902495, 2021). "Finally, the expression levels of GPC-1, 2, and 3 in the hepatitis group were related to the poor prognosis of HCC in the risk factor (alcohol consumption and hepatitis) subgroup (P < 0.05)." (PMID 33902495, 2021).
HIV-1 infection (1 paper, 2025). The type species of lentivirus and the etiologic agent of acquired immunodeficiency syndrome (AIDS). "Collectively, these findings implicate a cell surface protein susceptible to alkyl-CIMSS in restricting HIV-1 infection and identify GPC1 as a novel modulator of HIV-1 infection." (PMID 41278678, 2025). "Treatment of TMEM16F KO cells with alkyl-CIMSS also induced an increase in GPC1, which was associated with a significant increase in HIV-1 infection of the KO cells (p<0.05)." (PMID 41278678, 2025). "To explore whether TGF-β signaling contributed to the increase in HIV-1 infection associated with upregulation of GPC1, we treated GPC1 overexpressing cells or alkyl-CIMSS treated Jurkat-CCR5 cells with SB431542, a pharmacological inhibitor of TGF-β signaling." (PMID 41278678, 2025). "SB431542 reduced HIV-1 infection of both the GPC1 overexpressing and alkyl-CIMSS-treated Jurkat-CCR5 cells." (PMID 41278678, 2025). "Further, we demonstrate that the influence of GPC1 on HIV-1 infection is in part mediated by TGF-β signaling." (PMID 41278678, 2025). "Lentiviral introduced overexpression or knockdown of GPC1 demonstrated that increased levels of GPC1 promote HIV-1 infection." (PMID 41278678, 2025). "Whole cell proteomic and transcriptomic studies of alkyl-CIMSS treated cells identified increased expression of GPC1 as a candidate for mediating the enhancement of HIV-1 infection." (PMID 41278678, 2025). "The enhancing effects of GPC1 were independent of TMEM16F activation as alkyl-CIMSS upregulated GPC1 and partially restored the susceptibility of TMEM16F KO cells to HIV-1 infection." (PMID 41278678, 2025). "This hypothesis was confirmed by showing that overexpression of GPC1 also increased HIV-1 infection." (PMID 41278678, 2025). "GPC1 regulates multiple cell signaling pathways including TGF-β, which has been previously shown to promote HIV-1 infection." (PMID 41278678, 2025). "This notion was suggested by prior studies showing that GPC1 can signal through TGF-β, and TGF-β has been shown to promote HIV-1 infection by complex mechanisms, including upregulation of CCR5 and enhanced HIV-1 transcription." (PMID 41278678, 2025). "Lentiviral delivery of GPC1 overexpression and shRNA knockdown constructs reveal that the presence and absence of GPC1 independently of alkyl-CIMSS treatment significantly impact HIV-1 infection, with the effect on infection corresponding to GPC1 expression." (PMID 41278678, 2025). "In contrast, the same cell-impermeable pan-kinase inhibitor targets a different and as of yet unidentified molecule or molecules present on the cell surface, independent of viral exposure, which upregulate GPC1 to enhance HIV-1 infection." (PMID 41278678, 2025).
Hypertension (1 paper, 2021). The presence of chronic increased pressure in the systemic arterial system. "GCX expression, including Glypican 1, is inhibited in hypertension." (PMID 34692689, 2021).
hypertrophic cardiomyopathy (1 paper, 2024). A condition in which the myocardium is hypertrophied without an obvious cause. "Glypican-1 has been associated with cardiac voltage-activated K+ currents and LV hypertrophy, while obscurin associates with LV hypertrophy and hypertrophic cardiomyopathy." (PMID 39131907, 2024).
Insulin resistance (1 paper, 2019). Increased resistance towards insulin, that is, diminished effectiveness of insulin in reducing blood glucose levels. "Vitamin K epoxide reductase complex, subunit 1-like 1 (VKORC1L1), BTD, GPC1, MOCOS, GPC5, AKR1C4, and NMNAT2 are novel biomarkers for the development of insulin resistance." (PMID 30678306, 2019).
malignant mesothelioma (1 paper, 2020). A malignant neoplasm of the pleura or peritoneum, arising from mesothelial cells. "This has been demonstrated with SDC1 in malignant mesothelioma, and here we may be detecting similar effects on other HSPGs by simply modulating GPC1." (PMID 32180897, 2020).
muscular dystrophy (1 paper, 2019). Muscular dystrophy (MD) refers to a group of more than 30 genetic diseases characterized by progressive weakness and degeneration of the skeletal muscles that control movement. "Moreover, glypican-1 has recently been linked to the pathophysiology of a muscular dystrophy complicated by a myasthenic syndrome as well as of laminin α4, which has an important role in NMJ-integrity." (PMID 31133972, 2019).
Niemann-Pick disease (1 paper, 2017). A group of inherited, severe metabolic disorders in which sphingomyelin accumulates in lysosomes in cells. "In addition, we examined Glypican 1, a family member that has been connected with neurodegeneration in the context of Niemann-Pick Disease." (PMID 28103900, 2017).
non-small cell lung carcinoma (1 paper, 2024). A group of at least three distinct histological types of lung cancer, including non-small cell squamous cell carcinoma, adenocarcinoma, and large cell carcinoma. "The main objective of this study was to investigate the antitumor effect of a mouse anti-human glypican-1 (GPC1) monoclonal antibody (mAb) on non-small cell lung carcinoma (NSCLC) and associated molecular mechanisms." (PMID 38966167, 2024).
pancreatic neuroendocrine tumor (1 paper, 2017). Pancreatic endocrine tumor, also known as pancreatic neuroendocrine tumor (PNET), describes a group of endocrine tumors originating in the pancreas that are usually indolent and benign, but may have the potential to be malignant. "In addition, GPC1 was expressed in pancreatic ductal neoplasms, and also in pancreatic neuroendocrine tumors or solid-papillary tumors." (PMID 29245923, 2017).
preeclampsia (1 paper, 2020). Preeclampsia is a hypertensive disorder of pregnancy that is characterized by new-onset hypertension with proteinuria presenting after 20 weeks of gestation, and depending on mild or severe forms may initially present with severe headache, visual disturbances, and hyperreflexia. "The findings demonstrated that miR-125b significantly inhibited KCNA1 in trophoblast cells, and suppressed GPC1 expression in endothelial cells, suggesting KCNA1 and GPC1 may play distinct roles in the pathogenesis of preeclampsia." (PMID 32435510, 2020).
prostate adenocarcinoma (1 paper, 2024). "Cancers with the most significant decreased expression of GPC-1 were found in Skin Cutaneous Melanoma (SKCM, P = 7.36e−114), followed by Testicular Germ Cell Tumors (TCGT, P = 1.46e−51) and Prostate adenocarcinoma (PRAD, P = 4.32e−43)." (PMID 38982153, 2024).
Salmonella Infections (1 paper, 2024). Infections with bacteria of the genus SALMONELLA. "Among the KEGG terms, the result showed that GPC-1 was enriched with salmonella infection, endocytosis, and shigellosis with P value < 0.05, and these genes were mapped to neurotrophins signaling pathway, TNF signaling pathway, and sphingolipid signaling pathway." (PMID 38982153, 2024).
scrapie (1 paper, 2009). A fatal disease of the nervous system in sheep and goats, characterized by pruritus, debility, and locomotor incoordination. "In addition, we show that depletion of glypican-1 inhibits the formation of PrPSc in scrapie-infected cells, implying that glypican-1 is a novel cellular cofactor in prion conversion." (PMID 19936054, 2009). "Furthermore, we have shown that depletion of glypican-1 by siRNA knock down significantly inhibits the formation of PrPSc in a scrapie-infected cell line." (PMID 19936054, 2009).
Senile plaques (1 paper, 2021). Senile plaques are extracellular deposits of amyloid in the gray matter of the brain. "Likewise, glypican-1 (Gpc-1) seems to be predominant in senile plaques and cerebrovascular amyloid deposits in AD patients." (PMID 34454574, 2021).
serous cystadenoma (1 paper, 2022). A serous neoplasm in which the cysts and papillae are lined by a single layer of cells without atypia, architectural complexity or invasion. "Frampton’s finding showed that crExos GPC-1 could not discriminate between PDAC and benign pancreatic disease (IPMN, CP, and serous cystadenoma)." (PMID 36313694, 2022).
triple-negative breast carcinoma (1 paper, 2021). An invasive breast carcinoma which is negative for expression of estrogen receptor (ER), progesterone receptor (PR), and human epidermal growth factor receptor 2 (HER2). "In triple-negative breast cancer, low expression of GPC1 showed a positive effect on RFS." (PMID 33742285, 2021).
urothelial carcinoma (1 paper, 2019). A malignant neoplasm derived from the transitional epithelium of the urinary tract (urinary bladder, ureter, urethra, or renal pelvis). "It was found that the monoclonal antibody MIL-38 holds promise for diagnosis, drug delivery and targeted therapy, as it mediated the targeted binding of upconversion photoluminescent nanoconjugates to Glypican-1 positive urothelial carcinoma cells." (PMID 31816991, 2019). "In this study, UCNP were conjugated with anti-Glypican-1 monoclonal antibodies MIL-38 to target urothelial carcinoma cells T24." (PMID 31816991, 2019). "In this study, the specificity of anti-Glypican-1 antibody MIL-38 towards urothelial carcinoma cells was utilised for their targeted labelling by UCNP coupled to MIL-38 and termed targeted UCNP nanoconjugates." (PMID 31816991, 2019). "Conjugates have been shown to specifically attach to urothelial carcinoma cells with high expression of Glypican-1." (PMID 31816991, 2019). "Assessment of sensitivity and specificity of the binding of nanoconjugates UCNP@SiO2-LPG-MIL-38, was performed by incubation with urothelial carcinoma cells with high expression of Glypican-1 (T24) and urothelial carcinoma cells with low expression of Glypican-1 (C3)." (PMID 31816991, 2019).
virus infection (1 paper, 2017). "Cytometry assay showed that both AdmiR96 and AdmiR149 virus infection significantly decreased the percentage of GPC1+ exosomes in the supernatant of cultured HT‐29 cells (P < 0.001)." (PMID 28233416, 2017). "In HT‐29 cells, both AdmiR96 and AdmiR149 virus infection significantly inhibited GPC1 protein expression (P < 0.001)." (PMID 28233416, 2017).
tumor (185 papers, 2008 to 2026). "GPC1 expression was significantly associated with tumour size (p = 0.005) and TNM stage (p = 0.029)." (PMID 39823268, 2025). "Several supermere‐specific proteins, such as THBS4, SDC1 and GPC1, are implicated in tumor progression, cell adhesion and intercellular signaling and have been detected in tumor‐derived EVs in previous studies." (PMID 41039818, 2025). "In the present study, tumor size, venous invasion, stage progression, residual tumor, and distant metastatic recurrence were associated with high GPC1 protein concentration in preoperative plasma." (PMID 39300946, 2024). "Further study is needed to investigate the impact of selective inhibition of GPC1 with anti-GPC1 mAb on the crosstalk between tumor cells and tumor-associated fibroblasts in NSCLC." (PMID 38966167, 2024). "While research on MVs or large EVs in PDAC remains limited, a recent paper has been published, linking glypican-1 mRNA expression in EXOs and protein levels in tumor-associated MVs, presenting a dual biomarker signature for PDAC." (PMID 39698536, 2024). "GPC1, a cancer antigen, is a heparan sulfate proteoglycan that is linked to the cell surface by a glycosylphosphatidylinositol anchor and promotes tumor growth, metastasis, and invasion by acting as a co-receptor." (PMID 37509347, 2023). "In our study, GPC1 was remarkably upregulated in tumour samples and was screened as a risk factor for CRC patients’ OS (P = 0.003, HR = 1.043, CI:1.014–1.073)." (PMID 36895014, 2023). "In this study, a high proportion of GPC1-positive exosomes was associated with a larger tumor size and tumor burden." (PMID 36142190, 2022). "Lu’s study found that high levels of GPC-1 in tumor tissues were associated with poorer differentiation and larger tumor diameters in patients with PDAC." (PMID 36313694, 2022). "The level of GPC1-positive circulating exosomes was also associated with tumor burden and survival, with higher levels detected in distant metastases of patients." (PMID 36142190, 2022). "High GPC1 levels have been associated with poor pathological differentiation and larger tumor masses." (PMID 36142190, 2022). "Melo et al50 also reported that the levels of GPC1 on tumor‐derived exosomes were associated with the tumor burden and survival of pre‐ and post‐surgical patients." (PMID 32490335, 2020). "GPC1 has been implicated in tumor progression events, such as growth, angiogenesis, and metastasis, and has been especially studied in pancreatic cancer, glioma, and breast cancer." (PMID 30027065, 2018). "Higher GPC1 levels were associated with being male (P = 0.0186) and with worse tumor biological features, including poor pathological differentiation (P = 0.0005) and larger tumor sizes (P = 0.0331)." (PMID 28440066, 2017). "Our data suggest that GPC1 is associated with tumor growth and that targeting GPC1 with anti-GPC1 mAb represents a therapeutic strategy to decrease tumor growth in patients with GPC1-positive ESCC." (PMID 28445969, 2017). "Age, tumor location, and vascular invasion were associated with expression of GPC1 in a clinical cohort." (PMID 29245923, 2017). "Advanced T classification (p = 0.007), T3-T4 grouping (p = 0.001), positive NG2/CSPG4 transcript expression (p = 0.029), or GPC1 positivity in stromal cells (p = 0.007) were all conditions strongly associated with a high loco-regional tumour relapse rate." (PMID 25935541, 2015). "Notably, syndecan‐1 (SDC1) and glypican‐1 (GPC1) are well‐established modulators of the tumor microenvironment and are frequently associated with exosomal cargo in aggressive cancers." (PMID 41039818, 2025). "Immune lipoplex nanoparticle biochip assay showed GPC1 membrane protein expression in the microvesicle‐rich EV subpopulation, especially the tumor‐associated microvesicles, and Glypican1 (GPC1) mRNA expression in the exosomes‐rich (Exo)EV subpopulation served as a viable biomarker for PDAC." (PMID 39757782, 2025).
tumor (continued). "By capturing and characterizing GPC1 mRNA expression within an exosome‐dominated EV subpopulation (Exo), as well as its membrane protein expression on tumor‐associated microvesicles (tMV), we have unveiled a potential single‐gene, dual‐biomarker strategy for the diagnosis and prognosis of PDAC." (PMID 38204202, 2024). "Given the potential impact of anti-GPC1 mAb on the interaction between tumor cells and tumor associated fibroblasts observed in the in vitro model, the anti-tumor activity of anti-GPC1 mAb was evaluated and associated mechanisms were explored using an orthotopic A549 tumor xenograft model." (PMID 38966167, 2024). "Considering the potential impact on interactions with the tumor microenvironment, the expression of GPC1 has also been observed in cancer-associated fibroblasts (CAF) involved in stroma formation, which is associated with an immunosuppressive state that supports cancer progression." (PMID 38017492, 2023). "Multiple HSPGs and CSPGs core proteins and related enzymes were upregulated in GBM tumors relative to normal brain, including various genes previously implicated in tumor invasion and tumorigenesis and observed by the present study, including glypican 1, CSPG4, BGN, and AGRN." (PMID 35202840, 2022). "Based on TCGA data, we found that GPC1 was associated with the tumor stage." (PMID 36158119, 2022). "Therefore, the tubulin-polymerising inhibitor MMAF was successfully delivered to the GPC-1-expressing tumour cells via anti-GPC-1 mAb and caused mitotic arrest." (PMID 32152502, 2020). "We hypothesized that crExos GPC1 levels may also be associated with clinico-pathological features, and found that high crExos GPC1 expression was associated with larger tumor sizes (>4 cm)." (PMID 29721179, 2018). "Tumor burden was associated positively with levels of GPC1+ circulating exosomes." (PMID 30671023, 2018). "However, high pre-operative crExos GPC1 expression levels were associated with larger tumor sizes (>4 cm; P = 0.012)." (PMID 29721179, 2018). "We speculate that high α3(V)/GPC1 expression levels associated with human luminal A tumours may reflect particular importance of such expression to the growth properties of such tumours." (PMID 28102194, 2017). "Such growth advantage may be of particular importance to luminal A tumours, with which particularly high α3(V) and GPC1 expression levels are strongly associated." (PMID 28102194, 2017). "Moreover, immunoprecipitations from tumour extracts and analysis of FGF2 amounts associated with the ECM of WT/PyMT, KO/PyMT, and GPC1 knockdown tumour cells supported the conclusion that the three proteins interact in vivo." (PMID 28102194, 2017). "Thus, the difference in sensitivity to FGF2 between KO/PyMT and WT/PyMT tumour cells, caused by α3(V) ablation, is GPC1-dependent." (PMID 28102194, 2017). "Col5a3−/− MMTV-PyMT tumour cells had greatly reduced proliferative potential, apparently due to loss of interactions between α3(V) and the cell surface proteoglycan glypican-1 (GPC1), affecting ability of the latter to act as a co-receptor for mitogenic factors." (PMID 28102194, 2017). "High levels of GPC1 were associated with poorer differentiation and larger tumor diameters." (PMID 28440066, 2017). "GPC1 plays essential roles in regulating various signaling pathways involved in tumor cell proliferation, invasiveness, and tumorigenesis." (PMID 42196164, 2026). "This study introduces an innovative method for cancer immunotherapy utilizing genetically modified Escherichia coli Nissle 1917 (EcN) as an oral delivery mechanism for Glypican-1 (GPC1), a tumor-associated antigen." (PMID 40282924, 2025). "Regarding the IHC expression of GPC1 in the two tumor types, it was significantly higher in lung SCC compared to ADC." (PMID 39797955, 2025). "Glypican-1 (GPC1), a member of the HSPG family, is overexpressed in BC cells and is associated with tumor progression, while its expression is low in normal tissues." (PMID 40443562, 2025).